FAM25A (family with sequence similarity 25 member A)
Synonyms: bA96C23.5
Tractability: No criterion of Open Targets' tractability assessment is met for any kind of drug.
Gene: Protein-coding gene on chromosome 10 (87,020,294 to 87,024,730, forward strand). Ensembl gene ENSG00000188100.
Gene Ontology:
Molecular function: protein binding
Genetic constraint (gnomAD): Loss-of-function variants: 5 observed, 9.23 expected, observed/expected ratio (o/e) 0.54, 90% interval 0.28 to 1.14. That is too few expected variants to judge how well the gene tolerates losing a copy. Missense variants: 93 observed, 109.01 expected, observed/expected ratio (o/e) 0.85, 90% interval 0.72 to 1.01. Synonymous variants: 36 observed, 40.71 expected, observed/expected ratio (o/e) 0.88, 90% interval 0.68 to 1.17.
Homologues: Orthologues: chimpanzee FAM25A (100% identical), mouse Fam25a (80% identical), rat Fam25a (80% identical), guinea pig Fam25a (78% identical), dog FAM25A (71% identical). Paralogues in human: FAM25C (100% identical), FAM25G (100% identical).
Diseases named in the same sentence as FAM25A in open-access papers:
FAM25A is named in the same sentence as 2 diseases in open-access papers, as found by Europe PMC text mining. Sharing a sentence is not in itself a finding about the gene and the disease. The quoted sentences say what the papers report.
gingivitis (1 paper, 2022). A disorder involving inflammation of the gums; may affect surrounding and supporting structures of the teeth. "This review identified that exRNA has the greatest diagnostic potential, with four biomarkers (SPRR1A, lnc-TET3-2:1, FAM25A, CRCT1) displaying sensitivity of >71% and specificity of 100% in the assessed samples (p < 0.001) for gingivitis." (PMID 35453967, 2022).
FAM25A also shares sentences with these, for which no sentence is quoted: pancreatic cancer (1 paper).